CD4 (CD4 molecule)
Diseases named in the same sentence as CD4 in open-access papers (continued):
Sharing a sentence is not in itself a finding about the gene and the disease.
AIDS (continued). "The patient was diagnosed with PCP associated with AIDS after a high plasma HIV-RNA titer and low CD4+ cell count were confirmed." (PMID 37007317, 2023). "Opportunistic infection, type of ART medication used, CD4-count, and change in ART regimen change is significantly associated with musculoskeletal disorder among HIV/AIDS patients following ART." (PMID 37596525, 2023). "Trials exploring the efficacy of darunavir as a first-line treatment also included patients with low CD4 counts and AIDS-defining events, and they also reported good results in the long term." (PMID 37243208, 2023). "As an example, expression of immune checkpoint molecules PD-1 and TIGIT on CD4+ T cells was shown to increase with time during untreated infection and was inversely correlated with the CD4+ T-cell count during AIDS." (PMID 38420260, 2023). "Compared with previous studies, the patients we studied suffer from immunologic failure, and given the low CD4 count of the patients in our study, most are classified as stages 3 and 4 of AIDS." (PMID 37382253, 2023). "T cell count, especially the quantity of CD4+ T cells, plays an independent role in the evaluation of the disease progression of AIDS patients and can reflect the health conditions of the immune system." (PMID 37695104, 2023). "The patients who develop AIDS present low CD4 counts; therefore, they have reduced immunity and, consequently, become sicker and prone to opportunistic infections." (PMID 37341259, 2023). "Note that it is also possible to increase the CD4 + T cell counts of patients during the AIDS phase by the initiation of the ARTs." (PMID 37020854, 2023). "More specifically, AIDS individuals displayed the highest frequency of CD4low and the lowest CD4 count, which suggests a higher CD4 downregulation during AIDS." (PMID 38420260, 2023). "Independent of these general risk factors, having a low current CD4+ cell count, and to a lesser extent uncontrolled HIV replication and a prior AIDS diagnosis were also identified as risk factors." (PMID 37199566, 2023). "As most lethal cryptococcal infections occur in AIDS patients with insufficient CD4+ T cells, it is important to test the protective effect of ZNF2oe vaccination in a CD4-deficient animal model." (PMID 37338404, 2023). "All previous studies on TTV in HIV+ donors have been performed on chronically infected HIV+ donors and/or AIDS subjects, all displaying rather low CD4+ T cell counts." (PMID 37766337, 2023). "HIV viral load monitoring for HIV/AIDS cases with higher CD4 + counts at diagnosis is also necessary for ensuring improved long-term treatment outcomes under the scaling up of ART in the communities." (PMID 38049910, 2023). "The two main factors explaining the change in the number of CD4 after 6 months were the stage of AIDS and the number of CD4 at the beginning of cART." (PMID 38093984, 2023). "PLWH were divided in three categories based on CD4 cell-count at time of ART initiation: timely presentation (CD4>350cells/μL), late presentation (CD4 200-350cells/μL or >350cells/μL with AIDS-defining illness) and very late presentation (CD4<200cells/μL)." (PMID 36753495, 2023). "There is a also a conceptual merit for the use of our new measure of disease progression: if the slow CD4+ T cell decline during chronic infection starts at a higher level, it will take longer to reach the AIDS defining level of 200 CD4+ T cell ml−1 blood." (PMID 37161335, 2023). "Late initiation of ART was defined as having CD4 counts <200 cells/μl or having a clinical AIDS diagnosis at ART initiation." (PMID 38054578, 2023). "Several studies have shown that routine screening for Cr-Ag in AIDS patients with CD4 + lymphocyte counts < 100 cells/μl and interventions for antigen-positive patients can reduce the morbidity and mortality of CM." (PMID 37024795, 2023). "At the time of selection for this study, the CD4 counts for three cases of previously diagnosed AIDS were 847 cells/μL, 288 cells/μL, and 204 cells/μL." (PMID 37812611, 2023).
AIDS (continued). "CMVR is a common opportunistic infection with diverse clinical features in AIDS patients, preponderant in those who are male, homosexual, or with CD4+ T-cells <50 cells/μL." (PMID 37305416, 2023). "A proportion of these patients will have advanced HIV disease at diagnosis (defined as a CD4 count < 200 cells/μL or clinical AIDS)." (PMID 37470977, 2023). "Prevalence estimates were reported at 49.5% for late HIV diagnosis and 58.1% for late HIV presentation for care (defined as having a CD4 count < 350 cells/μL or clinical AIDS at the first contact at a treatment center participating in the ClinSurv cohort)." (PMID 37470977, 2023). "In fact, the current study showed that participants with AIDS and lower nadir CD4 counts had more complete study visits than participants with less advanced HIV." (PMID 35908270, 2023). "Research have shown that the incidence of postoperative sepsis in AIDS patients is 48.94%; When the CD4+ T lymphocyte count ≤100 cells/μL, the incidence of postoperative sepsis can be as high as 81.25%." (PMID 38126075, 2023). "Nonetheless, the present study estimated the DDD using the database of the national HIV/AIDS surveillance system by using the CD4 depletion model." (PMID 37139388, 2023). "HIV-1 disease progression to AIDS is characterized by dramatic depletion of CD4+ T cells including via pyroptosis and chronic inflammation accompanied by high levels of plasma cytokines including IL-1." (PMID 37417868, 2023). "The third edition Guidelines, issued in October 2015, recommended that ART should be initiated when the count of CD4+T cells is less than 500 cells/mm3 in people living with HIV/AIDS." (PMID 37679721, 2023). "When the MOS-HIV subscores were adjusted for CD4 and a history of AIDS, the group with high decisional conflict had predominantly lower general health perceptions and quality of life subscores than the group with low decisional conflict." (PMID 36859482, 2023). "To confirm such observations, we ran a multivariable regression model expressing the immune changes over time as a function of BL CD4+ T cell count and history of AIDS, time from HIV diagnosis, and time with HIV-RNA < 50 copies/mL before the switch." (PMID 37376522, 2023). "Boniatti and colleagues (2020) investigated early (within five days from enrolment) compared to late (after ICU discharge) ART start among ART-naïve HIV positive participants admitted to ICU in Brazil with low CD4 count or a AIDS-defining illness." (PMID 36963024, 2023). "At enrolment, median age was 35 years, 33.4% subjects had CD4 T-cell count ≥ 500 cells/μL, and 12.4% had an AIDS diagnosis." (PMID 38008809, 2023). "Median CD4 count was 24 cells/mm3, with histoplasmosis as the AIDS-defining condition in 88% and concomitant AIDS-defining conditions in 29%." (PMID 37839020, 2023). "First, the great part of the newly diagnosed patients had consistent CD4 lymphocytes depletion, implicating substantial immunosuppression, and 40% had an AIDS-defining condition." (PMID 37109543, 2023). "As a result, the expected time until AIDS depends not only on the CD4+ T cell decline, but also on the CD4+ T cell level at the end of primary infection." (PMID 37161335, 2023). "In AIDS patients, CD4+ T-cells are severely impaired, but they are crucial for vaccine-induced humoral immunity." (PMID 37376408, 2023). "The aim of this study was to describe the virological (viral load) and immunological (T-cell CD4) failure in patients infected with HIV / AIDS and under ARV treatment in a total of 1088 patients." (PMID 38223572, 2023). "Patients with CD4+ T cell recovery and a low CD4/CD8 ratio have increased immune activation and a higher risk of non-AIDS morbidity and mortality." (PMID 36672667, 2023). "Mp1p antigen screening can be an effective tool for more efficient diagnosis of Talaromycosis, especially in HIV/AIDS patients with low CD4+ counts." (PMID 38011216, 2023).
AIDS (continued). "When viral load levels increase, CD4 levels continue to decrease with cellular immunodeficiency, leading to AIDS and eventually mortality." (PMID 37887742, 2023). "The nadir CD4+T-cell count was 241 cells/μL, and 23.8% of the patients had been diagnosed with AIDS in the DTG plus RPV group and 15.7% in the DTG plus 3TC group." (PMID 37112915, 2023). "Although ART cannot completely cure HIV/AIDS, it can reduce viral replication and raise CD4 numbers." (PMID 37946846, 2023). "A proportion of these patients will have advanced HIV disease at the time of diagnosis (defined as CD4 count < 200 cells/μL or clinical AIDS)." (PMID 37896874, 2023). "And CD4+ T cell counts as a marker of acquired immunodeficiency syndrome (AIDS) progression have also been proven to correlate with cytopenia." (PMID 37575113, 2023). "This alternative measure is more comparable to the direct observation of the time until death or AIDS than the decline of CD4+ T cells alone." (PMID 37161335, 2023). "The CD4 count was significantly lower during AIDS compared to both recent and long-term infections (P =0.01)." (PMID 38420260, 2023). "Late presentation (LP) of HIV infection was defined as HIV diagnosis with a CD4 count < 350 cells/μL or an AIDS-defining event." (PMID 36895684, 2023). "HIV is dangerous because its presence in the body leads to a sharp decrease in the number of CD4 + T-lymphocytes, resulting in a state of acquired immunodeficiency, AIDS, in which the concentration of T-lymphocytes is 200 cells per microliter or less." (PMID 37048145, 2023). "People living with HIV/AIDS who had a CD4 count of 200–499 cells/mm3 were 2.69 times more likely to have poor sleep quality compared with those whose CD4 count was less than 200 cells/mm3." (PMID 37359994, 2023). "At HIV diagnosis, the median CD4 count was 284.0 cells/mm3 (IQR 192.0–462.0), 59.3% met late diagnostic criteria (CD4 count below 350 cells/mm3), and 9.1% had AIDS." (PMID 37373818, 2023). "Many studies have identified independent correlations between the CD8 cell counts or the CD4/CD8 ratio and the risk of mortality and non-AIDS events." (PMID 38124745, 2023). "HIV-1 mainly destroys the immune system by attacking host immune cells (mainly CD4+ T cells), so a marked reduction of circulating CD4+ T cells is a major feature of AIDS." (PMID 37465759, 2023). "HIV, the virus responsible for acquired immunodeficiency syndrome (AIDS), attacks explicitly CD4+ helper T cells and slowly wipes them out." (PMID 37789431, 2023). "The Chinese guideline of management of HIV/AIDS also recommends cotrimoxazole prophylaxis of CD4 < 200 cells/mm3 until CD4 > 200 cells/mm3 is achieved for longer than 3 months." (PMID 37351535, 2023). "Untreated HIV-1 infection progresses to acquired immunodeficiency syndrome (AIDS) as peripheral blood CD4+ T cells decrease to below 200 cells/uL, eventually leading to life-threatening opportunistic infections and cancer." (PMID 37955826, 2023). "A group of four macaques were challenged by IV injection with SHIV-AD8eo, a viral strain capable of maintaining chronic-phase viremia and inducing progressive CD4+ cell depletion and acquired immunodeficiency syndrome (AIDS)." (PMID 37626720, 2023). "Since the controllers resist the progression to AIDS, maintaining low levels of viral load and an adequate count of CD4+ T lymphocytes, it is directly reflected in a lesser impairment of their metabolism." (PMID 37457832, 2023). "The clinical pathologies that arise during CD4+ T cell absence, such as during AIDS progression or in several primary immunodeficiencies, highlights their importance in human health." (PMID 37892982, 2023). "The 3′A allele has shown a positive influence in delaying the progression to AIDS, and with higher rates of CD4+ TL decline and progression to AIDS." (PMID 36902388, 2023).
AIDS (continued). "It is essential to track the success of the given antiretroviral therapy by hindering the viral dynamics from the AIDS phase, i.e., by keeping the CD4 + T cell count as high as possible." (PMID 37020854, 2023). "Median p24+ cell frequencies were 72, 32, and 340/million CD4+ T cells during recent, long-term infections, and AIDS, respectively." (PMID 38420260, 2023). "In 1981, the first reported cases of Acquired Immunodeficiency Syndrome (AIDS) propelled intense further investigation into the function and characterization of the CD4+ T cell subset." (PMID 37892982, 2023). "Europe, the United States, and Australia have reported lower proportions of HIV late presenters despite using a higher cutoff of CD4 count <350 cells/mm3 or an AIDS-event at HIV diagnosis." (PMID 37351535, 2023). "In our sample, 27.8% presented criteria for AIDS according to the presence of an opportunistic infection and/or a CD4+ T cell count <200 cells/mm3." (PMID 37096666, 2023). "This trend translates into a lower CD4+/CD8+ ratio in the AIDS group up to week 48 of dual DTG plus 3TC therapy." (PMID 36851536, 2023). "Still, patients under study were deeply immunocompromised with a median CD4 count of 24 cells/mm3, a concomitant AIDS-defining condition in one third, which is quite similar to previous reports on HIV-associated histoplasmosis." (PMID 37839020, 2023). "Median CD4-nadir was 173/μl and a majority (66%) had a history of HIV-associated or AIDS-defining conditions." (PMID 37526898, 2023). "Some opportunistic pathogens can possibly contribute themselves to vasculitis development, especially among AIDS patients with CD4+ < 200/μL." (PMID 37468910, 2023). "The mean CD4+ count in HIV/AIDS patients with positive toxocariasis serology was 255.1 ± 21.6 cells/μL." (PMID 37138234, 2023). "People living with HIV/AIDS who have low CD4 and whose occupation is farmer or merchant should get special support." (PMID 37359994, 2023). "An inverted CD4/CD8 ratio and a low CD4 nadir have been associated with an increased risk of non-AIDS events." (PMID 36627565, 2023). "In conclusion, Mp1p antigen screening can be an effective tool for more efficient diagnosis of talaromycosis, especially in HIV/AIDS patients with low CD4+ counts." (PMID 38011216, 2023). "As indicated by the odds ratios (OR) of the first set of models, late HIV diagnosis, the presence of AIDS, and current age over 50 years are postulated as limiting factors in achieving an improvement in CD4, %CD4, CD8, and CD4/CD8 ratio." (PMID 36769822, 2023). "AIDS is defined as an HIV-1 induced depletion of peripheral blood CD4+ T cells below 200 cells/μL or due to the presence of an AIDS-defining illness (ADI) including persistent pneumonia, tuberculosis, or Kaposi’s sarcoma." (PMID 37892982, 2023). "There is a substantial drop in CD4+T cell counts in the acute phase of HIV-1 infection in contrast to the chronic phase, where a continued decline in CD4+T cells occurs and leads to AIDS." (PMID 37243203, 2023). "Severity in mpox has mainly been reported in PWH with low CD4+T-cell count and has been proposed to be considered an AIDS-defining event." (PMID 38004713, 2023). "The main change in AIDS is a progressive decrease in CD4 cell and their abnormal function, which ultimately results in a low immune function of the body." (PMID 37102652, 2023). "The DRV group differed from the DTG group for a slightly older mean age, a longer time since HIV diagnosis, a higher frequency of current AIDS-defining events, a lower baseline CD4 cell count and a higher baseline plasmatic viral load." (PMID 36992471, 2023). "AIDS is caused by HIV-1 (Human Immunodeficiency Virus-1) infection, and is characterized by the progressive loss of CD4+ T cells." (PMID 37892982, 2023). "Previous studies have focused on using the CD4:CD8 ratio as a marker of greater risk of cardiovascular events, non-AIDS defining cancers, diabetes, and hypertriglyceridemia." (PMID 36851599, 2023).
AIDS (continued). "Exosomes containing Nef can promote the secretion of itself, increase intracellular MVBs and induce apoptosis of CD4+ T cells, which contribute to the depletion of CD4+ T cells in the pathogenesis of AIDS." (PMID 37063897, 2023). "PWH who were more likely to remain in the study had more advanced HIV (i.e., AIDS status, lower nadir CD4) and greater incidence of HCV." (PMID 35908270, 2023). "Generally speaking, CD4+ lymphocytes decreased, which is the main development trend of malignant tumors, immunodeficiency diseases, and AIDS." (PMID 37336871, 2023). "CD4+ T cells from people with AIDS show the highest level of activation when compared to non-AIDS participants." (PMID 38420260, 2023). "A shedding study done in South Africa showed that persons living with HIV/AIDS with low CD4 counts (<200cells/μl) had significantly longer periods of SARS-CoV-2 shedding, ranging between 7 and 43 days, during the 2020 pandemic period in South Africa." (PMID 37253027, 2023). "Diagnosis with CD4 <200 cells/mmɜ with AIDS-defining conditions (HR = 2.75, 95%CI:1.52–4.97, p < 0.001) and non-integrase strand transfer inhibitor regimens (non-INSTI, HR = 1.80, 95%CI:1.01–3.24, p = 0.047) increased VF risk." (PMID 38140680, 2023). "A Wilcoxon rank sum test was conducted, revealing that 3 months after vaccination, AIDS patients with CD4+ T ≥ 350 had higher levels of neutralizing antibodies against the BF.7 strain than those with CD4+ T < 350 (p = 0.02)." (PMID 37376408, 2023). "Based on both the CD4+ T cell count after primary infection and CD4+ T cell decline, we estimate the time until AIDS." (PMID 37161335, 2023). "HIV-positive individuals often exhibit a high prevalence of opportunistic intestinal pathogens, and chronic AIDS patients with low CD4+ T cell counts frequently demonstrate polyparasitic infections." (PMID 37697423, 2023). "Duration of delayed diagnosis and age at the onset of infection in HIV patients using CD4 depletion model on the national HIV/AIDS surveillance system database (HASS)." (PMID 37139388, 2023). "C. neoformans and Cryptococcus deneoformans primarily cause infections in severely immunocompromised individuals, including patients with HIV/AIDS, especially those with CD4+ T-cell counts of <50 cells/μl." (PMID 37251371, 2023). "We selected studies in which the association of the CD4/CD8 ratio and/or CD8 counts with the incidence of non-AIDS events, including mortality, was reported." (PMID 37639938, 2023). "The development of combination antiretroviral therapy (cART) has achieved the suppression of viral replication and the increase in CD4+ T cell count in the majority of patients, leading to a significant decrease in morbidity of AIDS and mortality." (PMID 37608956, 2023). "Markedly, CD4+cells were detected up to 50 cells/μL in blood samples of AIDS patients by Magneto-ELISA34." (PMID 37463964, 2023). "Although CD4+ T cell count and HIV viral load are routinely monitored in HIV/AIDS patients, there are varying reports regarding the clinical relevance of CD4+ T cell counts." (PMID 37937297, 2023). "Human immunodeficiency virus (HIV) accelerates the production and destruction of CD4+ T lymphocytes, and it results in acquired immunodeficiency syndrome (AIDS)." (PMID 38116383, 2023). "HIV-1-specific T cells were frequently detected after long-term cART in AIDS patients with a lower CD4 count at pre-cART, while there was a tendency for a positive association of ΔCD4 with the frequency of positive T-cell responses under cART." (PMID 37877716, 2023). "The two main factors explaining the change in CD4 count after 6 months were the stage of AIDS and the CD4 count at the beginning of cART." (PMID 38093984, 2023). "The World Health Organization (WHO) recommends that ART should be initiated when the count of CD4+T cells is less than 500 cells/mm3 in people living with HIV/AIDS." (PMID 37679721, 2023).